FABP1 (fatty acid binding protein 1)
Diseases named in the same sentence as FABP1 in open-access papers (continued):
Sharing a sentence is not in itself a finding about the gene and the disease.
FABP1 also shares sentences with these, for which no sentence is quoted: Sepsis (21 papers); cardiovascular disease (11); COVID-19 (8); kidney (8); renal failure (8); anemia (6); kidney injury (6); injury (5); colorectal adenoma (4); necrotizing enterocolitis (4); Acute hepatitis (3); acute tubular necrosis (3); mucinous carcinoma of the ovary (3); alcohol fatty liver disease (2); breast neoplasm (2); chronic hepatitis (2); coronary artery disease (2); end-stage renal disease (2); glomerulonephritis (2); hepatoblastoma (2); hyperlipidemia (2); lung carcinoma (2); melanoma (2); polycystic kidney disease (2); pulmonary diseases (2); renal carcinoma (2); renal cell carcinoma (2); abdominal aortic aneurysm (1); acute coronary syndrome (1); acute liver failure (1).
A further 80 diseases each share a sentence with FABP1 in 1 paper.